ALB (albumin)
Diseases named in the same sentence as ALB in open-access papers (continued):
Sharing a sentence is not in itself a finding about the gene and the disease.
diabetes (continued). "Individuals with DM+C were more likely to present with high anion gap/metabolic acidosis, features of renal impairment, and low albumin/lymphocyte count than those with DM‐NC or those without diabetes." (PMID 34859617, 2022). "There were also positive correlations with serum insulin in diabetes and albumin (weak correlation each), but HDL-c was not correlated with biochemical parameters." (PMID 35462799, 2022). "In the Diabetes and Women's Health study, women with a GDM history had significantly higher estimated glomerular filtration rate and urinary albumin-to-creatinine ratio 9–16 years postpartum, indicating early stages of glomerular hyperfiltration and renal damage." (PMID 35237556, 2022). "Age, sex, BMI, diabetes, hemoglobin, and albumin were not significantly different between the subjects with and without cachexia." (PMID 35269531, 2022). "In 10 month-old mice, the amount of albumin that leaked in the neural retina was higher in Akt2fl/fl diabetic mice compared to nondiabetic controls, while Akt2 cKO lowered such diabetes-induced leakage." (PMID 36229454, 2022). "Otherwise, age, BMI, albumin, diabetes mellitus, ischemic heart disease and pStage did not correlate with the incidence of anastomotic leak significantly." (PMID 33930090, 2021). "In the present study, through multivariate Cox regression and LASSO analysis, we identified that albumin, lymphocyte count, CA19-9 and diabetes might be independent prognostic indicators for predicting OS of patients with resected PDAC." (PMID 34136406, 2021). "This association remained unchanged after adjusting for the following factors: diabetes, previous history of CVD, eGFR, hemoglobin, albumin, D/P creat, BMI, renin-angiotensin system inhibitors use, icodextrin use, high-glucose fluid use, diuretics use, dosage of PD fluid and peritonitis rate." (PMID 34237104, 2021). "Those with and without detectable urine albumin had similar rates of self-reported diabetes (13% vs 8%, p = 0.42), hypertension (43% vs 31%, p = 0.17) and similar systolic blood pressure." (PMID 34570768, 2021). "Treatment with angiotensin-converting enzyme inhibitors (ACEi) or angiotensin II receptor blockers (ARBs) prevents the progression of CKD in both people with and without diabetes and reduces urine albumin excretion." (PMID 34532145, 2021). "The data for patient 2 showed low ischemia-modified albumin level (<=72.50 μ/ml), surgical treatment, and no indication of diabetes, all of which aided the negative prediction." (PMID 34604356, 2021). "The change in venular calibre correlated with initial white cell and neutrophil counts (p both < 0.01), but not with initial CRP, serum albumin, gender, hypertension, diabetes, smoking history dyslipidaemia, haemoglobin level or renal function (p all NS)." (PMID 34446820, 2021). "In our study, we also found that patients with diabetes who have retinopathy, compared with those without retinopathy, had greater urinary albumin excretion." (PMID 34970109, 2021). "For treating diabetes, Levemir® and Victoza®, myristic acid derivatives of human insulin or glucagon-like peptide 1 (GLP-1), act as long-acting peptides by binding to the fatty acid binding sites on circulating albumin in order to control glucose levels." (PMID 34771316, 2021). "Of these, 35,251 (70.3%) were considered optimized with BMI <40 kg/m2, albumin ≥3.5 g/dL, no current tobacco use, and no diabetes." (PMID 34277906, 2021). "The multivariate logistic regression analysis showed that dietary calorie intake adequacy <60% was an independent predictor of worse clinical outcomes after adjustment for age, BMI, NYHA functional class III, diabetes, LVEF, serum albumin, eGFR, and log BNP in chronic HF patients." (PMID 33800134, 2021). "With respect to the long-term outcomes, there were no new occurrences of diabetes and the serum albumin levels were normalized after surgery." (PMID 33602183, 2021).
diabetes (continued). "The persistent hyperglycemic environment during diabetes favors nonenzymatic albumin glycation (Maillard reaction), generating Amidori GA." (PMID 33800425, 2021). "In this study, our constructed recombinant anti-IL-6R fusion proteins (VHH-0031), by linking 2 single domain chains against the pro-inflammatory cytokine receptor (IL-6R) and human serum albumin (HSA) respectively, presents potent renoprotective effect in diabetes both in vivo and in vitro." (PMID 34054555, 2021). "Patients with CIN non-recovery were older, more frequently to have anemia, diabetes, worse renal function, higher baseline of NT-proBNP, urine albumin levels, and lower LVEF." (PMID 33675474, 2021). "Gender, diabetes mellitus, neoadjuvant CRT, albumin, and tumor distance from the anal margin were statistically significant in comparison between the two groups, while differences between the groups in the remaining assessed factors were not statistically significant." (PMID 34456630, 2021). "There was no statistical difference in age, baseline renal function, serum albumin, levels of blood lactate and procalcitonin, and proportion of morbidities (hypertension, diabetes, and pre-CKD) on admission between patients with or without AKI progression." (PMID 34906098, 2021). "The following adjustments were performed in regression models: model 1, crude model; model 2: model 1 + age and sex; model 3, model 2 + BMI, serum albumin, and hemoglobin; model 4, model 3 + phosphorus, PTH, diabetes, hypertension, and cardiovascular disease; model 5, model 4 + eGFR and CRP." (PMID 34934591, 2021). "Subjects with diabetes had significantly higher phosphate, albumin, C-reactive protein, brain natriuretic peptide and sclerostin levels (61.1 vs 39.3 pmol/L, P = 0.035), compared to those without diabetes." (PMID 34644326, 2021). "However, diabetes, high PG-SGA score, and low postoperative albumin are an imbalance of nutritional status." (PMID 32461995, 2020). "Risk of death was assessed in Cox models adjusted for age, sex, race, heart rate, BMI, smoking, diabetes duration, insulin use, HbA1c, eGFR, brain natriuretic peptide (BNP), urine albumin/creatinine ratio, treatment allocation and prior coronary revascularization." (PMID 33046070, 2020). "Furthermore, we had insufficient data on certain clinical parameters regarding duration of diabetes, concurrent medications particularly ACEI/ARB and different methods using to measure urine protein or albumin excretion as an endpoint." (PMID 32045421, 2020). "Female sex and advanced age, with hypertension, diabetes, lower LVEF, and lower hemoglobin level were more common in the CKD group (p < 0.001) compared with the normal group, as were preoperative stroke, atrial fibrillation, and lower albumin level (p < 0.05)." (PMID 32727495, 2020). "The measured free 25(OH)D correlated markedly with 25(OH)D3 (r = 0.92, p < 0.05) and serum albumin (r = −0.4, p < 0.05) in the control group; in the diabetes group, there was no such relationship (r = 0.42 and 0, respectively, p > 0.05)." (PMID 33352890, 2020). "T-AN and H-AN levels were strongly correlated with the albumin level in subjects with/without diabetes." (PMID 32985540, 2020). "In addition to hyperglycemia, other glycemic markers have been used for the diagnosis of diabetes mellitus (DM), including fructosamine, glycated albumin, hemoglobin A1c (HbA1c), and 1,5-anhydroglucite, each with its own limitation, if we consider cost for countries in development." (PMID 33159100, 2020). "The most obvious link between CV risk and NFS is the fact that this score is constituted of factors like age, BMI, ALT, AST, platelets, albumin, and the presence or absence of diabetes, all of which reflect metabolic and inflammatory processes." (PMID 32283679, 2020). "These reinforces the kidney contribution to diabetes development and highlights insulin and albumin dynamics prior and regardless of the development of diabetes." (PMID 32850773, 2020).
diabetes (continued). "Albumin levels in 25 patients (62.50%) without diabetes and 23 patients (57.50%) with diabetes were lower than normal (85 g/L), but the differences between the groups were not statistically significant (P = 0.08)." (PMID 33376750, 2020). "By contrast, age, gender, diabetes, albumin, anastomosis, bleeding, and operation time did not have significant effects." (PMID 32646466, 2020). "In this retrospective cohort study, all incident patients with ESRD and NS who started PD from 1 February 2006 to 31 December 2017, were matched with patients without NS using propensity scores based on age, sex, diabetes mellitus status, and serum albumin." (PMID 32686569, 2020). "However, hidden hypocalcemia remained a significant risk factor for the primary outcome after adjustment for a history of diabetes, PCI/CABG and heart failure, ALP, iPTH, pH, BMI, and albumin." (PMID 32157180, 2020). "Inverse univariate associations were found for age, BMI, smoking, cotinine excretion, SBP, DBP, coffee consumption, hs-CRP, GlycA, diabetes, glucose, total cholesterol:HDL cholesterol ratio, cystatin C, albumin excretion, and use of antihypertensives, antidiabetics, and statins (all P < 0.05)." (PMID 32899820, 2020). "In univariable analysis, age, male sex, dysrhythmia, chronic obstructive pulmonary disease, pulmonary hypertension, malignancy, diabetes, ASA classification, hemoglobin levels, albumin levels, map50_dur and bis40map50_dur were found to be potential risk factors for 90-day mortality." (PMID 32795266, 2020). "Individuals with and without diabetes were compared to those who had urinary albumin excretion after physical stress, and then, the differences between these two groups of individuals were identified." (PMID 33467285, 2020). "We performed supplemental analysis by further adjusting the full Cox model for the following variables: current cigarette smoking, hypertension diagnosis, diabetes mellitus diagnosis, BMI, WC, WHR, LDL, HDL, triglycerides, hsCRP, RDW, MCV, albumin, AGR, ALP, eGFR and BUN." (PMID 32764826, 2020). "There was significant difference between DVT and non-DVT patients regarding gender, age (both in continuous and categorical variable), past diabetes mellitus, past any surgery, injury mechanism, ASA grade, TP, ALB, FBG, LYM, RBC count, HGB level, HCT, and D-dimer level." (PMID 32581237, 2020). "When compared to subjects with WFA+-M2BP ≥ 1.0 and those with WFA+-M2BP < 1.0, albumin levels and platelet counts were significantly lower in subjects with WFA+-M2BP ≥ 1.0, and the presence of diabetes mellitus was significantly higher in subjects with WFA+-M2BP ≥ 1.0." (PMID 33375190, 2020). "Recent reports have shown that potential risk factors for PPH following PD include body mass index (BMI), intraoperative transfusion, portal vein resection, POPF, preoperative biliary drainage, absence of diabetes, and lower serum albumin level." (PMID 32998260, 2020). "It includes TBIL, ALB, Scr, ALT, diabetes, and HCC as variables predicting prognosis." (PMID 32879889, 2020). "The long-term effect of PA on urinary excretion of albumin in patients with and without diabetes is still unclear." (PMID 33467285, 2020). "Multivariate logistic regression analysis showed that ischemia-modified albumin was positively correlated with CCC formation [OR = 1.190,95% CI (1.092–1.297),P < 0.001], while diabetes was negatively correlated with CCC formation [OR = 0.285,95% CI (0.094–0.864), P < 0.05]." (PMID 32641068, 2020). "These techniques have allowed several applications of AI into the diagnosis and management of diabetes such as the diagnosis of microalbuminuria in type II diabetes patients without the need to measure urinary albumin levels." (PMID 32192211, 2020). "Most importantly, we compared the outcomes of these patients with those of the matched controls without NS using PSs based on age, sex, diabetes mellitus, and serum albumin." (PMID 32686569, 2020).
diabetes (continued). "The global MACE criterion was associated with MetS in univariate (OR 2.13; 95CI 1.56–2.92; p < 0.01) as well as multivariate analysis (OR 1.85; 95CI 1.24–2.75; p < 0.01) after adjustment for diabetes, LDL-cholesterol, smoking, age, sex, BMI, statin treatment and serum albumin." (PMID 32792012, 2020). "Furthermore, another study reported that in patients with diabetes, the combination of cilnidipine with a RAS inhibitor had an additive effect in suppressing urinary albumin excretion." (PMID 33489354, 2020). "Following the stratification of groups by gender and the presence/absence of diabetes, serum albumin levels, GNRI, and PhA were positively correlated, while OH, OH/ECW, and ECW/ICW were negatively correlated with serum zinc levels in all groups." (PMID 33086501, 2020). "These associations were independent of age, gender, UACR, diabetes and CRP, body mass index, waist-hip ratio (WHR), cholesterol and triglycerides for serum bilirubin, albumin, and haemoglobin but not for concentration of ALT." (PMID 33261565, 2020). "Nearly one-third of patients had diabetes and were more likely to have their blood pressure and albumin-to-creatinine ratio monitored than those without diabetes." (PMID 32183127, 2020). "Inclusion criteria were diagnosis of type 2 diabetes mellitus, absence of diabetic retinopathy, and a 24 hours urinary albumin measurement in the last 3 months at the primary health-care center." (PMID 32185073, 2020). "In this study, we determined a significant negative correlation between ECD and diabetes duration, HbA1c levels and the urinary albumin-creatinine ratio of patients in the diabetic group." (PMID 32493325, 2020). "Compared with the lower groups (Q1 and Q2), the higher groups (Q4 and Q5) had higher values of DBP, TC, TG, LDL-C, FBG, albumin, and SUA; were more likely to have stroke and diabetes; and were more likely to take antihypertensive drugs and glucose-lowering drugs." (PMID 33183311, 2020). "Similar results were observed when we replaced diabetes with inflammatory markers (i.e., C-reactive protein [CRP], tumor necrosis factor alpha [TNF-α], interleukin-6 [IL-6], and monocyte chemoattractant protein-1 [MCP-1]) or serum albumin concentration." (PMID 32661200, 2020). "In contrast, growth-inhibiting protein 25 (GIG25/AACT/SERPINA3), albumin (ALB), and transthyretin (TTR) were expressed at lower levels in normal patients with abdominal obesity (Group 2), prediabetes (Groups 3 and 4), and diabetes (Groups 5 and 6) than in normal patients (Group 1)." (PMID 31504048, 2019). "After adjusting for age, sex, diabetes, history of CVD, hypertension, eGFR, BMI, CCI, white blood cells, hemoglobin, platelet, serum albumin, total cholesterol, uric acid and the use of lipid-lowering agents, the TG/HDL-C ratio remained associated with all-cause and CV mortality." (PMID 31729985, 2019). "The results of the current study of participants with mild-moderate CKD in the absence of diabetes have demonstrated novel factors positively associated with HOMA-IR, including serum albumin, HbA1c, and uric acid." (PMID 30786864, 2019). "Two PQIs focusing on prescribing of RAAS inhibitors in patients with micro-albuminuria and diabetes were not operational valid in this population because of the limited availability of albumin/creatinine ratios (indicators 3 and 5)." (PMID 31326925, 2019). "The PhA, intracellular water/body weight (ICW/BW), and albumin levels were significantly lower in patients with diabetes than in those without diabetes." (PMID 31775231, 2019). "Baseline NLR was related to age, hypertension, serum triglycerides, total serum cholesterol, CVD history, urine albumin to creatinine ratio (ACR), chronic kidney disease-mineral and bone disorder (CKD-MBD), hyperlipidemia rate, diabetes, and estimated glomerular filtration rate (eGFR)." (PMID 30876475, 2019).
diabetes (continued). "As expected, patients with high CAC (> 100 AUs) were older, higher prevalence of clinical CVD and diabetes, had higher levels of systolic BP, hsCRP, TNF, IL-6 and, lower levels of triglycerides, creatinine, serum albumin, total testosterone in male,and T-score of tBMD." (PMID 30777028, 2019). "After multivariate adjustment, older age, longer duration of PD, presence of diabetes, comorbid CVD, use of 2.5% glucose dialysate, higher CRP, lower BMI, and lower albumin and phosphate levels continued to be independently associated with increased HR for all-cause mortality." (PMID 30850727, 2019). "Although the blood-brain barrier is relatively impermeable to larger proteins under both normal physiological conditions and in the setting of diabetes, a previous study suggested that a GLP-1/albumin fusion molecule exhibited anorectic effects after peripheral administration." (PMID 31404283, 2019). "The PhA was also positively correlated with serum protein and albumin levels in patients both with and without diabetes." (PMID 31775231, 2019). "Unfortunately, there is a point that oxidative stress is a key mechanism for albumin glycation in individuals without diabetes." (PMID 30858941, 2019). "After further adjustment for eGFR, urinary albumin excretion, BMI, systolic blood pressure, hs-CRP, presence of diabetes, smoking, alcohol use, and use of antihypertensives (model 2), the association between TSAT and mortality persisted (HR, 0.84; 95% CI 0.75–0.95; P = 0.004)." (PMID 31170159, 2019). "The albumin–peptide fusion product, Albiglutide (Tanzeum®), is a recombinant fusion protein with two tandem copies of modified human GLP fused to albumin that was approved to improve glycemic control with adults with type 2 diabetes mellitus." (PMID 29973504, 2018). "In the multivariate Cox regression analysis, the significance of serum Angpt-2 associated with all-cause mortality in model was lost when adjusting for age, male gender, diabetes and components of MIAC syndrome (hs-CRP, serum albumin, background VC and background AVD) (p = 0.3)." (PMID 30445969, 2018). "Metabolomic screening identified 1,242 metabolites, out of which 111 differed significantly between progressors and non-progressors after adjustment for age of diabetes onset, baseline glycosylated hemoglobin A1c (HbA1c), and albumin excretion rate (AER)." (PMID 30217994, 2018). "Pearson's correlation between uVDBP levels and the different clinico-laboratory parameters showed its significant correlation with family history of diabetes, HbA1c %, LDL-c, total serum protein levels, and urinary albumin/creatinine ratio (r = 0.309, 0.584, −0.244, −0.202, and 0.775, resp)." (PMID 29850609, 2018). "HIV status, diabetes status, culture TTP (log10TTP), serum albumin, number of grade 3 or 4 TB symptoms, BMI, age, and ethnicity were found to have a statistically significant effect on the radiological severity of chest images by univariable analysis in the group with cavity disease." (PMID 29779492, 2018). "From stage A to stage D, patients had a trend to be older and have lower LVEF, blood pressure, cholesterol, triglyceride, hemoglobin, albumin, and eGFR, but have higher heart rate, BNP levels, and incidence of diabetes mellitus, chronic kidney disease, and atrial fibrillation." (PMID 30405858, 2018). "In this study, 1067 participants without diabetes and with urinary albumin-creatinine ratio <300 mg/gCr (normo- or microalbuminuria) who underwent an annual health examination in 2004 were enrolled and observed for 5 years." (PMID 29624611, 2018). "As expected, DN-vehicle mice developed robust progressive albuminuria (expressed as urinary albumin to creatinine ratio (ACR)) and AS-IV prevented the development of diabetes-induced albuminuria in a dose-dependent manner without altering the blood glucose levels and body weight." (PMID 28761152, 2017).